TNF (tumor necrosis factor)
Diseases named in the same sentence as TNF in open-access papers (continued):
Sharing a sentence is not in itself a finding about the gene and the disease.
COVID-19 (continued). "COVID-19 patients with high NLR were reported to have increased inflammatory markers such as interleukin-6 and tumor necrosis factor-alpha (TNF-α)." (PMID 37363430, 2023). "Severe manifestations of COVID-19 may be partly accounted for by an autoimmune reaction mediated by a dysregulated network of circulating proinflammatory cytokines and inflammatory markers, including IL-1β, IL-6, IL-2, IL-8, IL-17, TNF-α, C-reactive protein, D-dimer, and antibodies." (PMID 37712090, 2023). "The hyper-proinflammatory cytokine storm, including interleukin-6, nuclear factor kappa B (NF-κB), and TNF-α released from SARS-CoV-2-infected macrophages and monocytes, results in multi-organ injury/failure and the development of severe COVID-19." (PMID 36674700, 2023). "We explored other potential combinations: IL-1ꞵ/TNF-α (p = 0.003), IL-1ꞵ/MIP-1α (p = 0.003), and TNF-α/MIP-1α (p = 0.103), where the first two combinations correctly classify 90.9 and 80.0%, respectively, of the post COVID-19 cases." (PMID 37894054, 2023). "Other studies have shown that the administration of infliximab (anti-TNF-α antibody) reduced IL-6 and CRP levels in COVID-19 cases." (PMID 37854602, 2023). "TNF-α positively correlated with inflammatory CD14+CD16+ and patrolling CD16+ monocytes in pregnant women with acute COVID-19, while negatively correlating with classical CD14+ monocytes and activated NK cells." (PMID 37036008, 2023). "Indeed, studies of patients with COVID-19 have reported the increment of inflammatory monocytes and neutrophils, a sharp decrease in lymphocytes, and an inflammatory milieu containing interleukin (IL)-1β, IL-6, and tumor necrosis factor (TNF) in severe disease." (PMID 36703213, 2023). "The mediators IL-1β, IL-6, IL-10, TNF-α, IL-8/CXCL8, IL-1RA, IL-18/IGIF, and sTNFR1 were all increased in patients with COVID-19 and followed the rate of elevation as clinical worsening progressed." (PMID 36851766, 2023). "We also examined the expression of previously reported inflammatory cytokines (TNF, IL6, IL1B, CCL3, CCL4 or CXCL2) produced by circulating monocytes in patients with COVID-19." (PMID 37363730, 2023). "Through stimulation with the recombinant SARS-CoV-2 S protein in whole blood, we identified a signature for COVID-19 based on the cytokines IFN-γ, IL-2, IP-10, IL-1β, IL-6, IL-8, and TNF." (PMID 37018291, 2023). "This study aimed to investigate the roles of caspase-1, caspase-3, and TNF-alpha expressions in the placenta of pregnant women with both preeclampsia and COVID-19, COVID-19, and preeclampsia and to determine whether preeclampsia with COVID-19 damages the placenta." (PMID 37362630, 2023). "Patients with severe COVID-19 showed significant increases in cytokines, including IL-2, IL-7, IL-10, GSCF, IP10, MCP-1, MIP1A and TNF-α, with the characteristics of a cytokine storm." (PMID 37112613, 2023). "In COVID-19, patients with confirmed bacterial infections, blood level of neutrophils, CRP, ferritin, IL-1β, IL-2R, IL-6, and TNF-α were higher than the upper limits of the normal values with significant differences, while lymphocyte was significantly lower." (PMID 37771749, 2023). "SARS-CoV-2 infection triggers extensive production of pro-inflammatory molecules such as CRP, TNF-α, IL-1β, IL-6, MIP-1α, IP-10 and IL-10 by activated inflammatory monocytes and neutrophils recruited into the lungs of COVID-19 patients." (PMID 37854602, 2023). "These include interleukin-1 (IL-1), IL-6, IL-18, IL-10, interferon gamma (IFN-γ) and tumor necrosis factor-alpha (TNF-α) secreted by T helper type 1 (TH1) and other cells during the inflammatory process of COVID-19." (PMID 37447302, 2023). "As reported in our prior study, at 13 months after discharge, 11.6% of the HCWs with severe COVID-19 had elevated IL-6, and more than 98% had normal levels of the remaining five cytokines (IFN-γ, IL-10, IL-2, IL-4 and TNF-α)." (PMID 36908474, 2023).
COVID-19 (continued). "In co-infected patients:↑ TNF-α, MIP-1β, and IL-9 compared with COVID-19-only.↑ TNF-α, IL-1β, IL-17A, IL-5, FGF-basic, and GM-CSFcompared with TB-only.↓ specific response to SARS-CoV-2 and Mtb." (PMID 37662901, 2023). "At baseline, there were significantly increased frequencies of CD8+ T cells expressing IFN-γ, TNF-α, and IL-17A in MIS-C compared to children with COVID-19 and other infectious diseases." (PMID 38116577, 2023). "Flow cytometry also allowed the identification of lymphoid and myeloid cells producing cytokines such as TNF-α, IFN-γ, and IL-17, which are among the most important mediators of COVID-19 immunopathogenesis." (PMID 37048165, 2023). "The PPI network revealed that IL-6, MAPK1, TNF, and IL1B were the main targets of bitter almond-licorice to interfere with COVID-19." (PMID 38018195, 2023). "Incubation of platelets from COVID-19 patients with monocytes from healthy donors triggers the release of IL-1β, IL-6, IL-8, MIP-1α, MCP-1, TNF-α, PF4, and PDGF, and elevated levels of these factors were observed in clinical samples from COVID-19 patients." (PMID 38069209, 2023). "In the current study have been studied the relation between the levels of serum IL-10, TNF-α, INF-γ and TLR-4 and the presence of lymphopenia in COVID-19 patients group." (PMID 36864077, 2023). "Therefore, TNF inhibitors could be a promising treatment for severe COVID-19 patients." (PMID 37081046, 2023). "Expression levels of IL-6, TNF-α, IFN-γ, IL-10, IL-12p70, IL-1β, IL-8, IL-13, IL-2, IL-7, IL-17A, IL-5 and IL-7 were measured in saliva and serum pairs obtained from the COVID-19 patients with available baseline symptoms information." (PMID 36846089, 2023). "Research has shown that environments with high concentrations of TNF-α and IFN-γ can induce cell death by way of pyroptosis or apoptosis, either of which increases tissue damage and mortality in cases of COVID-19." (PMID 36979888, 2023). "Overproduction of cytokines, including IL-17, IL-7, IL-1β, IL-9, IL-2, IL-10, TNF-α, GM-CSF, G-CSF, IFN-γ, MCP1, MIP1A, MIP1B, CXCL10 and CXCL8, by monocytes and macrophages has been reported in severe COVID-19 cases." (PMID 36793739, 2023). "MMP-7, TGF-β, CCL2, CCL-3, CXCL-10, G-CSF, IFN gamma, IL-10, IL-2, IL-4, IL-6, IL-7, TNF-α, IL-6, and IGF-1 were studied for their correlation with mortality in all 40 COVID-19 patients." (PMID 36286038, 2022). "MAIT cells showed enrichment for TNF signaling and KRAS across COVID-19 groups and γδ T cells for cell cycle pathways." (PMID 35216673, 2022). "Particularly, monocytes from patients with acute COVID-19 secreted reduced G-CSF, MIP-1α, MIP-1β, MCP-1, TNF-α and IL-2 levels upon bacterial challenge." (PMID 35007290, 2022). "In the early recovery phase of COVID-19, patients who continued to develop PACS generally had higher levels of inflammatory biomarkers including TNF-α and interferon-inducible protein 10 (IP-10)." (PMID 36466841, 2022). "In the moderate COVID-19 group, NEAT1 was negatively correlated with oxygen but positively with age, TUG1 expression, CCL2, TNF-α, and IL-6 expression." (PMID 35982898, 2022). "Bacterial and endotoxin translocation in COVID-19 induces a significant increase in several markers of systemic inflammation, such as IL-6, IL-1b, IL-8, MCP-1, IP-10 and TNF-a." (PMID 35630492, 2022). "Anti-inflammatories, however, do by definition attenuate the pro-inflammatory cytokines responsible for the inflammatory process, including TNF-α and IFN-γ, which are two cytokines responsible in the defense mechanisms of both TB and COVID-19." (PMID 35320917, 2022). "Such interleukins as IL-1β, IL-6, IL-17A, TNFα, and monocyte chemoattractant peptide (MCP)-1 were identified in patients with severe COVID-19." (PMID 35213582, 2022). "Cytokines, such as IL-1β, IL-6, IFN-γ-induced protein 10 (IP-10), TNF-α, IFN-γ, macrophage inflammatory protein-1α and-1β (MIP-1α and-1β), and vascular endothelial growth factor (VEGF) are raised in COVID-19 patients." (PMID 36439786, 2022).
COVID-19 (continued). "There was a significant increase in the concentration of 40 cytokines/chemokines in a conditioned medium, including TNF-α, IFN-α, IL-6, and IL-1a, which corresponded to the cytokine profile in patients with severe manifestation of COVID-19." (PMID 36290634, 2022). "For example, the ratios of TNF-α/IL-5, IFN-α/IL-10, IL-6/IL-5, TNF-α/IL-4, and IFN- γ/IL-5, were lower (≈24-, 23-, 20-, 10-, and 10-fold) in COVID-19 ICU patients as compared with HC subjects." (PMID 36363785, 2022). "The elevated concentrations of tumor necrosis factor (TNF) and interleukin 1 (IL-1) seen in severe COVID-19 accentuate these phenomena." (PMID 36420234, 2022). "The same study also showed positive correlation between TNFα and PCT which was in keeping with our data in the COVID-19 cohort." (PMID 35500008, 2022). "The NF-κB upregulates the production of IL-1, IL-6, tumor necrosis factor (TNF)-α, and interferon (IFN)-α, which are the central cytokines involved in the hyperinflammatory response in patients with COVID-19." (PMID 35337387, 2022). "A recent study demonstrated a negative association between the total count of T cells, CD4+, and CD8+, and the TNF-α and IL-6 levels in ICU patients due to the COVID-19." (PMID 35456120, 2022). "Of the 16 mediators elevated in early COVID-19 compared with healthy controls, 11 decreased over time (CCL3, CCL4, TNF-α, IL-6, CCL13, IL-4, IFN-α2a, CXCL10, CXCL11, IL-2, and IL-12)." (PMID 35397798, 2022). "Higher plasma levels of proinflammatory cytokines such as IL-1, IL-2, TNF-α, GM-CSF, and MCP1 have been reported in COVID-19 patients." (PMID 35687545, 2022). "Overall, these findings identified the combined effect of elevated TNF-α, IFN-γ and IL-4 plasma levels in critically ill COVID-19 patients as some of the potent drivers of decreased antibacterial effector functionality of myeloid immune cells." (PMID 35007290, 2022). "Our results suggest that the TNFα.AG genotype seems to be related to symptomatic forms of the disease, which could be explained considering that TNFα mediates in many symptoms such as fever, dry cough, muscle weakness and multiple organ disfunction, all of which are present in COVID-19." (PMID 37521833, 2022). "The ratios of IFN-γ/IL-4, IL-12/IL-4, IFN- γ/IL-9, TNF-α/IL-4, IFN- γ/IL-5 and IL-12/IL-9 were lower ((≈30-, 11-, 8, 4-, 4-, and 3- fold differences respectively) in COVID-19 ICU patients as compared to HC subjects." (PMID 36363785, 2022). "COVID-19 moderate patients, compared to HD, also presented a high percentage of IFN-γ+IL-2+TNF+ and IL-2+TNF+." (PMID 35887351, 2022). "In agreement, COVID-19 severe patients show increased plasma concentration of IFN-α, IFN-γ, IL-6 and TNF-α early after the disease onset." (PMID 35844604, 2022). "The chest CT image of COVID-19 patients showed ground-glass opacity, and compared with healthy adults, the plasma concentrations of IL-1β, IL-7, IL-8, IL-9, IL-10, IFN-γ, TNF-α, and VEGF of COVID-19 patients were all upregulated." (PMID 35874688, 2022). "The frequencies of CD4+ and CD8+ T cells producing IFN-γ, TNF-α and IL-2 in response to SARS-CoV-2 Spike peptides were measured in randomly selected COVID-19 naïve healthy adults six months after the first vaccine dose." (PMID 36389704, 2022). "Consistently, TNF-α and IFN-γ were found prominently upregulated in the sera of patients with severe COVID-19, which was related to a phenomenon called cytokine storm or also viral sepsis." (PMID 35581387, 2022). "It has been reported that monocytes appear to produce more tumor necrosis factor alpha (TNF-α) and interleukin-10 (IL-10) in COVID-19 patients." (PMID 35690714, 2022). "From this search, we identified 6 cytokines that are critically involved in the pathogenesis of COVID-19 induced ARDS lung injury (IL-1β, IL-2, IL-6, IL-8, IL-10, and TNFα)." (PMID 35033181, 2022).
COVID-19 (continued). "Given the increased levels of TNF and IFNG in the plasma of patients with COVID-19, we inferred that TNF- and IFNG signaling pathways were likely to be activated in SARS-CoV-2-infected hBMECs." (PMID 35705998, 2022). "A decrease in natural killer T and B cells and increased expression of IL-2, IL6, IL10, TNF-α, and interferon-γ (INF-γ) were observed in the COVID-19 pathophysiology." (PMID 35656183, 2022). "In clinical applications, it has been found that severe COVID-19 patients presenting with ARDS lead to an increase in pro-inflammatory factors, most notably interleukin 1β (IL-1β), interleukin-6 (IL-6), and TNF." (PMID 35774402, 2022). "Recent works describe vitamin D deficiency affects cytokine synthesis, such as IL-6, IL-8, IL-12, TNF alpha, and IFN-gamma, altering cytokine storm in severe COVID-19 patients." (PMID 36293182, 2022). "Then, the most used class of drugs in this cohort is represented by the anti-TNF drugs and this made it possible to study their effect on RMD patients affected by COVID-19." (PMID 35891442, 2022). "However, in the COVID-19 context, the greater availability of tryptophan will allow for its metabolism through the kynurenine pathway, whose metabolites will induce the expression of the pro-inflammatory IL-1β, IL-10, TNF-α, IL-6 by AHR, further increasing the local and systemic inflammation." (PMID 36293182, 2022). "The SARS-CoV-2 spike protein enhanced the expression of ACE2 in Beas-2B cells, and the cytokines IL-4 and IL-13 were repressed, whreas TNF-α, IL-12, and IL-17 increased ACE2 expression in Beas-2B cells, which reflects the different risks of severe COVID-19." (PMID 35287354, 2022). "Lymphocytopenia is negatively correlated with increased serum levels of tumor necrosis factor alpha (TNF-α), IL-6 and IL-10 and postmortem examinations of COVID-19 patients revealed lymphocyte depletion and spleen necrosis in parallel with lymphocyte death." (PMID 35453524, 2022). "We identified 69 core COVID-19, EHF, and puerarin targets and signaling pathways, including NF-κB, IL-17, TNF, TLR, and HIF-1." (PMID 35663983, 2022). "The CS of severe influenza and COVID-19 concurs in elevated PRR- and inflammasome-induced cytokines, such as TNFα, IL-1β, and IL-6, revealing a persistent innate inflammatory reaction that is detrimental to the host." (PMID 35674675, 2022). "As compared to healthy donors, Vδ1+ T cells from COVID-19 patients spontaneously expressed TNF-α and IL-17, while unstimulated Vδ1+ T cells from recovered COVID-19 patients preferentially expressed IFN-γ, but also significant levels of TNF-α and IL-17." (PMID 36359845, 2022). "IL-1β, IL-6, IL-8, TNFα and CRP in the hospitalised patients with COVID-19 (n = 76) was higher (all p<0.0001) compared to the healthy volunteers." (PMID 35500008, 2022). "Analysis of cytokine and chemokine expression levels revealed higher IL-1β, IL-6, TNF, and CCL2, CCL3, CCL4, and CCL7 in severe COVID-19 BALF compared to moderate disease." (PMID 35401519, 2022). "COVID-19 has been associated with an exuberant activation of the host immune system and the excessive production of proinflammatory cytokines, such as IL-1, IL-2, IL-6, IL-10, IL-12, IFN-γ, TNF-α, among others, which may cause tissue injury, particularly on the lungs." (PMID 35090394, 2022). "TNF, GAPDH, MAPK3, MAPK1, EGFR, CASP3, MAPK8, mTOR, IL-2, and MAPK14 are important targets for YQS in COVID-19 treatment." (PMID 35340244, 2022). "On the other hand, lower circulating levels of IL-6, TNF-α, IL-α, and CCL4 were observed in the asymptomatic group of pregnant women with COVID-19 than healthy pregnant women." (PMID 36016660, 2022). "There is evidence that many pro-inflammatory cytokines and chemoattractant are elevated in COVID-19 patients, including IL-1β, IL-6, IL17, TNF-α, GM-CSF, and IFN-γ." (PMID 36034704, 2022).
COVID-19 (continued). "Many studies have revealed that patients with severe COVID-19 infections have higher levels of cytokines (TNF-α, IFN-γ, IL-2, IL-4, IL-6 and IL-10) than control individuals, especially during the characteristic COVID-19 cytokine storm." (PMID 35320917, 2022). "Stimulation with zoledronate increased TNF-α, IFN-γ, and IL-17 expression in Vδ2 T lymphocytes from both healthy donors and COVID-19 patients, but Vδ2+ T lymphocytes from these latter expressed significantly more IFN-γ and IL-17 compared to healthy donors." (PMID 36359845, 2022). "Recent studies have indicated that IL-6, TNF-α, and IFN-γ were intensely elevated in COVID-19 patients and had become a significant feature of COVID-19 diseases deterioration." (PMID 36034662, 2022). "Recent study reported mucosal-associated invariant T (MAIT) cells in particularly are highly activated in COVID-19 patients, and corelated with cytotoxicity by producing IFN-γ, Granzyme B, TNF-α cytokines, and with the severity and mortality of SARS-CoV-2." (PMID 36825215, 2022). "In particular, in the literature, it has been seen that anti-TNF drugs, widely used in the therapy of IBD, have a potential protective effect against COVID-19 symptoms due to a higher production of Tregs and, consequently, of anti-inflammatory cytokines." (PMID 36615826, 2022). "Our group reported that severe COVID-19 was associated with defects in T cell production of IFN-γ and monocyte TNF-alpha production and others reported weak CD8 T cell responses to COVID-19 antigen and impaired DC function." (PMID 35421120, 2022). "In our ICU cohort, males had higher TNFα, PCT and longer ICU stay with COVID-19 compared to females." (PMID 35500008, 2022). "Morphometry-based microscopic analysis revealed that the immunohistochemical reaction generated by antibodies against TNF-α, IL-1β, IL-15, IL-6, MCP-1, CD8, CD20, and CD45 was significantly different between the COVID-19 group and the control group." (PMID 34463916, 2022). "PG is associated with an increase in proinflammatory cytokines, including interleukin-12 (IL-12), IL-23, tumor necrosis factor (TNF)-alpha, and IL-6 9, which are also involved in the pathogenesis of COVID-19." (PMID 35600185, 2022). "The inflammatory cytokines TNF-α and IFN-γ play critical roles in COVID-19 pathogenesis through their induction of cell death." (PMID 36366521, 2022). "Second, the lack of detection results of glycosylated hemoglobin A1C, insulin level, TNF-α, IFN, IL-1β, and other cytokines limited the deeper assessment of glycemia and immune dysfunction in COVID-19 patients with T2DM." (PMID 37359706, 2022). "Clinical investigations have revealed that the vaccines trigger human antibody and Th1 cell response, which increases blood levels of IL-2, TNF-α and interferon (IFN)-gamma as a response to COVID-19 viral antigen." (PMID 35755518, 2022). "An overview of the literature indicates that IL-6, IL-2, IL-7, IL-10, granulocyte colony-stimulating factor (G-CSF), IFN- γ, inducible protein (IP)-10, TNF-α, MCP-1, macrophage inflammatory protein (MIP)-1α play a crucial role in the pathogenesis of COVID-19." (PMID 35619180, 2022). "An exaggerated release of pro-inflammatory cytokines, such as TNF-α, IL-6, IL-1, IL-8, and MCP-1, or “cytokine storm syndrome”, has been observed in severe COVID-19 patients." (PMID 35889352, 2022). "IL-6, IL-5, GCSF, IL-2, TNF-α, GMCSF, and IFN-γ were identified as COVID-19-related distinguishable cytokines, but only one (IL-12p70) was detected in the noninfected people." (PMID 35967091, 2022). "Since IL-6 was found elevated in COVID-19, it is of great interest to explore the combined effect of IFN-γ, TNF-α, with IL-6 on inflammatory cell damage." (PMID 36034662, 2022). "Severe COVID-19 patients admitted to intensive care unit showed higher level of pro-inflammatory cytokine including MCP1, MIP1α, IL2, IL7 and TNFα." (PMID 36369012, 2022).